KRAS (KRas proto-oncogene, GTPase)
Diseases named in the same sentence as KRAS in open-access papers (continued):
Sharing a sentence is not in itself a finding about the gene and the disease.
thyroid cancer (continued). "However, research focusing on mutation profile, including the presence of KRAS and EGFR mutations in addition to BRAF mutations in thyroid cancer, is still rarely described, particularly in Indonesia." (PMID 36510281, 2022). "However, data on Kirsten rat sarcoma virus (KRAS) and EGFR mutations in thyroid cancer in Indonesia remain unavailable, except for BRAF-V600E, the most common BRAF gene mutation." (PMID 36510281, 2022). "Our study highlights the frequent BRAF, KRAS, and EGFR mutations in thyroid carcinomas." (PMID 36510281, 2022). "Nearly half of the BRAF-V600E negative thyroid carcinoma samples harbored either KRAS or EGFR mutations." (PMID 36510281, 2022). "BRAF, KRAS, and EGFR mutations in recurrent thyroid cancer may benefit from targeted therapies and further study on these mutations with their risk of recurrence, distant metastasis, and overall prognosis in thyroid cancers may be required." (PMID 36510281, 2022). "We discovered that either KRAS or EGFR mutations can be found in nearly half of the BRAF negative thyroid carcinoma samples." (PMID 36510281, 2022). "Therefore, our results raise the question about the clinical utility of BRAF, KRAS, NRAS, and TERT promoter mutation analysis using ctDNAs of patients with thyroid cancers." (PMID 33915745, 2021). "Even though results of direct comparison of dPCR and NGS in BRAF detection are not available in thyroid cancer it seems that dPCR can have a lower limit of detection compared to NGS in case of KRAS mutation." (PMID 31810221, 2019). "Multiple molecular abnormalities have been described in thyroid cancers arising from ovarian teratomas, including point mutations in BRAF (V600E and K601E) 67% of cases and KRAS and NRAS as well as loss of heterozigocity in the PTEN region and ret/PTC rearrangements." (PMID 27882257, 2016). "In PDX models of colorectal and thyroid cancers, we observed significant inhibitory effect of the combination of selumetinib and KRT-232 on tumor growth across a spectrum of MAPK genomic backgrounds, including BRAF, KRAS, and NRAS mutations, compared to single-agent treatment with either drug." (PMID 35075200, 2022). "Analysis of single-cell sequencing data revealed that BRAF, EIF1 AX, KRAS, PIK3 CA, and TERT are significantly up-regulated in various immune cells within thyroid cancer, underscoring their potential regulatory roles in the immune microenvironment." (PMID 40450370, 2025). "This approach identified significant dependencies on key genes/proteins such as KRAS, NRAS, PABPC1, PPP2R1A, STAG2, and BRAF in thyroid cancer cell lines, underscoring their potential as critical therapeutic targets." (PMID 40297138, 2025). "The results revealed significant increases in the expression of BRAF, EIF1 AX, KRAS, PIK3 CA, and TERT genes across all types of immune cells in thyroid cancer, indicating their variability and potential regulatory roles in the immune microenvironment." (PMID 40450370, 2025). "For instance, only two known cancer genes were found to be mutated in over 5% of thymomas (MUC16 and HRAS), testicular germ cell tumours (KRAS and KIT), and thyroid carcinomas (BRAF and NRAS)." (PMID 37550388, 2023). "Many somatic genetic alterations, including those in BRAF, HRAS, KRAS, NRAS, PTEN, and HER1, have had fundamental roles in the tumorigenesis of thyroid carcinoma." (PMID 31655978, 2020).
thyroid cancer (continued). "Many somatic genetic alterations including those in BRAF, HRAS, KRAS, NRAS, PTEN, and HER1 have been revealed to play fundamental roles in the tumorigenesis of thyroid carcinoma." (PMID 27833153, 2016). "This study aimed to analyze KRAS and EGFR mutation profiles in BRAF-V600E negative thyroid cancer samples." (PMID 36510281, 2022). "Gene mutations were found in the NRAS, KRAS, BRAF, and KIT genes and were similar to those in thyroid carcinoma, but some patients (37.5%) did not exhibit any gene mutations." (PMID 33763376, 2021). "Interestingly, coexistence mutations (both KRAS and EGFR mutations) were found in 1 of our BRAF negative thyroid carcinoma sample." (PMID 36510281, 2022). "The limitation of the current study may be that we failed to prove the clinical utility of BRAF, KRAS, NRAS, and TERT promoter mutation as circulating markers in early-staged thyroid cancers distinguishing from benign thyroid lesions or healthy individuals." (PMID 33915745, 2021). "In conclusion, this study demonstrated that KRAS/SOS-1 inhibition could be a promising therapeutic target for the treatment of ATC and highlighted BAY-293 as an innovative molecule that needs further research to fully evaluate its efficacy in the field of thyroid cancer." (PMID 40141222, 2025).
hepatocellular carcinoma (84 papers, 2001 to 2026). A malignant tumor that arises from hepatocytes. "The presence of a KRAS mutation indicates that this tumor may exhibit molecular characteristics distinct from classic hepatocellular carcinoma." (PMID 40161114, 2025). "Binding and localizing with KRAS protein in the cytoplasm of human HuH-7 hepatoma cells, KRASIM inhibits the growth and proliferation of HCC cells." (PMID 38622617, 2024). "For example, KRASIM is a 99-aa microprotein expressed in hepatocellular carcinoma cells, whose overexpression reduces the level of KRAS." (PMID 33054771, 2020). "The proliferation capacity of KRAS‐mutant hepatocellular carcinoma cells is notably enhanced." (PMID 40390765, 2025). "Moreover, TNS4 expression was significantly increased in hepatocellular carcinoma and intrahepatic cholangiocarcinoma and was positively feedback-regulated by KRAS and SOX17 to stimulate migration and proliferation." (PMID 37328854, 2023). "Specifically, Vav1 synergizes with KRAS mutations to promote pancreatic cancer, while GEF–H1 facilitates hepatocellular carcinoma (HCC) metastasis by modulating RhoA‐dependent cytoskeletal changes." (PMID 41020039, 2025). "For instance, hepatocellular carcinoma (HCC) frequently exhibits 2 to 10 fold amplification of oncogenes such as Cyclin D1, CDKN1A, KRAS, and MDM2." (PMID 41515655, 2026). "KRAS G12V promotes steatosis and prevents hyperplasia in hepatocellular carcinoma (HCC)." (PMID 39806421, 2025). "KRASIM specifically binds to KRAS protein, and overexpression of KRASIM reduces the level of KRAS protein, leading to inhibition of ERK signaling pathway activity in hepatoma cells." (PMID 38877495, 2024). "The transcript levels of KRAS and KRAS1P correlate directly in prostate cancer, neuroblastoma, retinoblastoma, and hepatocellular carcinoma (HCC), which illustrates a proto-oncogenic role of KRAS1P in cancer." (PMID 34489556, 2022). "In hepatocellular carcinoma, NRAS expression is markedly upregulated in hepatocellular carcinoma tissues and cell lines; the combined inhibition of KRAS and NRAS reduces the resistance of hepatocellular carcinoma to sorafenib." (PMID 35339759, 2022). "For instance, KRASIM, the microprotein coded by the lncRNA NCBP2-AS2 has been found to suppress expression of KRAS and inhibit ERK signaling in hepatocellular carcinoma cells." (PMID 35139853, 2022). "Research confirmed that hsa-miR-622 was downregulated in hepatocellular carcinoma, resulting in dysregulation of CXCR4 and KRAS." (PMID 30777071, 2019). "In hepatocellular carcinoma (HCC), KRAS overexpression correlates with tumor aggressiveness." (PMID 40390765, 2025). "A 99-aa micropeptide named KRASIM encoded by lncRNA NCBP2-AS2, discovered through ribosome profiling and notably differently expressed in normal hepatocytes and hepatocellular carcinoma (HCC) cells, has been shown to interact with KRAS and inhibit ERK signaling in HCC cells." (PMID 39311199, 2024). "Previous work has shown that there is a specific increase in expression of CTLA4, a negative regulator of T-cell receptor signaling, during tumor progression in a KRAS-driven murine PDAC model and that induction of MYC in a model of hepatocellular carcinoma elevates CTLA4 expression on T-cells." (PMID 38365788, 2024). "Similarly, spheroids from human induced hepatocytes (generated from umbilical cord fibroblasts) could be differentiated into hepatocellular carcinoma (HCC) through Myc activation or into iCCA thorugh Kirsten Rat Sarcoma (KRAS) activation." (PMID 32235647, 2020).
hepatocellular carcinoma (continued). "This study aimed to investigate whether and how F-box and leucine-rich repeat 6 (FBXL6) regulates KRAS and KRASG12D activity in hepatocellular carcinoma (HCC)." (PMID 38124228, 2023).
viral infection (81 papers, 2005 to 2026). "This study aimed to explore the potential relationship between viral infections and gastrointestinal (GI) malignancies, focusing on the presence of KRAS G12D mutations." (PMID 39673361, 2024). "As for CVB3, it has been found that KRAS mutation results in compromised IFN-I production in response to viral infection in human lung epithelial cells, contributing to the permissiveness of KRAS-mutant lung adenocarcinoma cells to CVB3 infection." (PMID 34198859, 2021). "We examined KRAS mutations in the context of HPV and EBV infection to clarify the potential correlations between viral infection and genetic changes that occur within cells." (PMID 39673361, 2024). "This study needs to describe TLR3 at the molecular level in the process of re virus infection and reproduction mechanism, and special emphasis on the condition of KRAS‐mutant CRC, in search of a better method for the treatment of CRC with KRAS mutations." (PMID 29658188, 2018). "Some cases have been linked to viral infections, including Epstein–Barr virus, cytomegalovirus, human herpesviruses, and human immunodeficiency virus, as well as somatic mutations in genes such as NRAS, KRAS, MAP2K1 and ARAF." (PMID 41321345, 2025). "In addition, the investigation also showed that the effective expression of the host TLR3 was established by establishing a robust innate immune response with the KRAS‐mutant HCT116 cell line 79, which inhibited the potential of the virus infection." (PMID 29658188, 2018). "For example, overexpression of mutant KRAS and virus infection may not entirely reflect the mechanisms of malformation in human bAVMs." (PMID 39576014, 2024).
glioblastoma (77 papers, 2012 to 2026). The most malignant astrocytic tumor (WHO grade IV). "GSEA demonstrated that the risk score is significantly associated with the immune response, neurological response, KRAS signaling pathway and glioblastoma‐related tissues." (PMID 40561176, 2025). "Here, HROG05, a glioblastoma model harboring a KRAS mutation, turned out to be highly susceptible, while other cell lines were resistant to low concentrations of the AKT inhibitor." (PMID 36013437, 2022). "HROG05 cells are the only patient-derived glioblastoma model in our study that harbors a mutation in the protooncogene KRAS (G12D), a G protein that drives the activation of downstream pathways." (PMID 36013437, 2022). "HER2 gene amplification has been shown in glioblastoma multiforme in correlation to KRAS and NRAS mutations." (PMID 31952211, 2020). "For example, MGMT methylation is common, but KRAS mutations are relatively rare in glioblastoma." (PMID 27643594, 2016). "MM (pink) and glioblastoma (GBM) had both the highest frequency of KRAS A146 mutations while LZTR1 exhibited the strongest tumor suppressor effects." (PMID 41542462, 2026). "For example, KRAS signaling is essential for the maintenance of glioblastoma growth maintenance in mice, suggesting that inhibition of KRAS leads to tumor apoptosis." (PMID 39432011, 2025). "Here, we studied platinum-based chemosensitivity of long-term cultures of human glioblastoma from the perspective of KRAS expression, by using CDDP and MEK-inhibitor." (PMID 38225605, 2024). "Particularly, chemo treatment with cisplatin induces viability and apoptotic changes in glioblastoma cells in vitro, and KRAS proteins can reprogram cell state when ectopically expressed." (PMID 38225605, 2024). "Nevertheless, glioblastoma is considered KRAS-driven cancer due to its essential role in mouse malignant gliomagenesis." (PMID 38225605, 2024). "In the current study, we examined the KRAS gene involvement in platinum-based chemotherapy in human glioblastoma." (PMID 38225605, 2024). "Endogenous high KRAS expression was assessed at transcriptional (qPCR) and translational levels (WB) in a panel of primary and long-term glioblastoma cultures." (PMID 38225605, 2024). "Primary human glioblastomas show high mRNA expression of KRAS compared to long-term cultures (Figure_S4)." (PMID 38225605, 2024). "Following these mutations, KRAS and PIK3CA activate their downstream signaling pathways out of control and cause immoderate cell division and survival in glioblastoma cells." (PMID 35194440, 2021). "They found a NRAS mutation in 11 oligodendrogliomas, 2 KRAS mutations in 16 anaplastic oligodendrogliomas, and 2 KRAS mutations and 2 NRAS mutations in 226 glioblastomas." (PMID 34525976, 2021). "Another report suggested that KRAS signalling is essential for the maintenance of glioblastoma in mice, and inhibition of KRAS expression result in tumour apoptosis." (PMID 34525976, 2021). "In the KRAS-driven glioblastoma mouse model, autophagy blocked Atg7, Atg13, or Ulk1 by shRNA; inhibited the occurrence and growth of tumors; and extended the survival of mice." (PMID 33194668, 2020). "In particular, the KRAS oncogene is strongly involved in tumourigenesis in glioblastomas, although KRAS mutations are almost absent in malignant gliomas." (PMID 38637419, 2024). "From these results, we conclude that, at least in U251MG glioblastoma cultures, the overexpression of an oncogenic KRAS mutations modulate chemoresistance in vitro, not necessarily coupled with effect on proliferation/viability." (PMID 38225605, 2024).
glioblastoma (continued). "On the other hand, a recent study showed that overexpression of miR-424 strongly suppressed cell proliferation and migration rate in glioblastoma cells, by targeting genes such as KRAS, RAF1, and MAP2K1, from the epidermal growth factor receptor (ERBB) signaling pathway." (PMID 37047673, 2023). "Moreover, we highlight differential drug sensitivities and relative chemoresistance in glioblastoma cell lines with enhanced KRAS programs." (PMID 35013227, 2022). "Moreover, TERTp mutation tended to co‐occur with EGFR, KRAS, and MET in glioblastoma." (PMID 39804195, 2025). "In addition, the ectopic expression of a constitutively active form of KRAS (KRASG12V) may influence the apoptotic response of glioblastoma cells to cisplatin treatment." (PMID 40498028, 2025). "For example, gene expression signatures in colon adenocarcinoma (COAD) and glioblastoma (GBM) stratified tumors with aberrant KRAS and NF1 function, respectively." (PMID 29617658, 2018). "We found that glioblastoma (GBM) cells expressing patient-derived Kirsten rat sarcoma (KRAS) or phosphoinositide-3-kinase (PI3K) active mutants showed enhanced cell death under ischemia-mimetic conditions in vitro and were more likely to develop into necrotic tumors in vivo." (PMID 39805854, 2025). "Representative examples include case 3 (KRAS-mutant metastatic CRC post 6 lines of therapy) and case 15 (glioblastoma with hypermethylated MGMT promoter and multiple amplifications)." (PMID 40973166, 2025). "Still, in case of glioblastoma multiforme, HER2 was identified to be a part of cluster 1 also involving other top hub nodes of proto-oncogenes KRAS, HRAS and NRAS." (PMID 31952211, 2020). "This latter exerts a tumor suppressive function by inhibiting proliferation and malignancy of glioblastoma cells by targeting both NRAS and KRAS and by modulating microglia activation through TLR7." (PMID 33287106, 2020). "The endogenous expression of KRAS is increased in response to cisplatin treatment, and the inhibition of MEK may modulate the sensitivity of glioblastoma cells to cisplatin." (PMID 40498028, 2025). "KRAS signalling necessarily relies on ERK/MEK signalling and, MEK-inhibitors as single agent or in combinatorial setting are at the leading-edge treatment for many cancers, including glioblastoma." (PMID 38225605, 2024). "Indeed, FAK inhibition has been found to improve the radiation sensitivity in HNSCC, KRAS mutant NSCLC, and glioblastoma multiforme." (PMID 32705304, 2021). "In addition to a wide spectrum of cancer models, including glioblastoma, pancreatic, breast, and bladder cancers, 9-ING-41 has already been tested on wild-type KRAS CRC cell line HT-29 and recently on a panel of CRC cell lines." (PMID 34955846, 2021). "MerTK activates the STAT3/KRAS and SRC signaling cascades in glioblastoma multiforme (GBM)." (PMID 41195524, 2025). "The control over KRAS expression and activity in glioblastomas suggests that let-7 can regulate RAS activity even without oncogenic mutation and that this may be a general phenomenon related to the interactions between tumour suppressor genes (let-7) and proto-oncogenes (KRAS)." (PMID 38637419, 2024).